FOXC2 (forkhead box C2)
Diseases named in the same sentence as FOXC2 in open-access papers (continued):
Sharing a sentence is not in itself a finding about the gene and the disease.
Distichiasis (13 papers, 2007 to 2025). Double rows of eyelashes. "Mutation of the FOXC2 gene is associated with lymphedema in combination with distichiasis, defined as the presence of a second row of eyelashes emerging from the Meibomian glands." (PMID 37241126, 2023). "Over thirty FOXC2 mutations have been described as affiliated with distichiasis-lymphedema syndrome, and phenotypic expressivity is more common amongst female mutation carriers than males." (PMID 37241126, 2023). "Two novel dominant mutations in forkhead box protein C2 (FOXC2) have been associated with distichiasis in humans." (PMID 33256610, 2020). "Our data indicate that either loss or gain of FOXC2 function is deleterious, causing hyperplasia or hypoplasia respectively in patients with primary lymphedema-distichiasis." (PMID 27276711, 2016). "However, additional larger clinical studies are required to definitely elucidate correlations between FOXC2 different mutations and the morphologic changes of lymphatic system, and with distichiasis." (PMID 27276711, 2016). "The association of FOXC2 mutation function and distichiasis is less clear however." (PMID 27276711, 2016). "The FOXC2 haplo-insufficient state is associated to hyperplasia and distichiasis in mice." (PMID 27276711, 2016). "Le gène en cause FOXC2 (Forkhead Box C2) localisé en position 16q24.3, participe à l'embryogenèse du système lymphatique et vasculaire, d'où l'appellation de lymphœdème-distichiasis." (PMID 26090013, 2015). "Systemic dysregulation of FOXC2 has been found to promote defects in lymphatic vasculature and hereditary lymphedema-distichiasis syndrome, which presents as distichiasis (double rows of eyelashes) and lower-limb lymphedema that develops in adolescence." (PMID 39473610, 2024). "The complete list of genes regulated by FOXC2 is not known and these mutations only explain the disease in two families suggesting that other unexplained genetic mechanisms for distichiasis in humans may exist." (PMID 33256610, 2020). "While FOXC2 (ECA3) did not fall within a region of association in this GWAS, variants in this gene have been associated with distichiasis in humans, thus it was investigated as a candidate gene for equine distichiasis." (PMID 33256610, 2020).
colorectal cancer (12 papers, 2016 to 2025). A primary or metastatic malignant neoplasm that affects the colon or rectum. "Furthermore, MRTX1133 suppresses progression of KRAS G12D-mutated colorectal cancer by inducing ferroptosis via the METTL14/LINC02159/FOXC2 axis." (PMID 40746552, 2025). "This is supported by our observations in colorectal cancer patient data in which FOXC2-target genes are overall enriched in the CMS4 “mesenchymal” subtype." (PMID 37499655, 2023). "For examples, ectopic expression of the FOXC2 accelerates the development, proliferation and growth of tumors in colorectal cancer." (PMID 27027443, 2016). "In published studies, expression of FOXC2 has been shown to promote colorectal cancer metastasis, is necessary for the full metastatic phenotype of the 4T1 mouse model and is sufficient to promote cancer stem cell-like properties and metastatic activity in transformed human mammary epithelial cells." (PMID 35406526, 2022). "Our core FOXC2-target genes correlate with endothelial genes across cell lines from diverse tumor types and patient samples and stratify survival in CMS4 colorectal cancer, mesenchymal ovarian cancer, and renal cancer." (PMID 37499655, 2023). "FoxC2 promote epithelial mesenchymal transition (EMT) and colorectal cancer metastasis through the Akt/GSK-3β/Snail Pathway." (PMID 27027443, 2016). "This may be explained by some studies that have found the overexpression of Foxc2 enhances proliferation and inhibits apoptosis through activation of MAPK and AKT pathways in colorectal cancer." (PMID 29202800, 2017).
primary lymphedema (12 papers, 2015 to 2024). A congenital condition that results in swelling in the arms or legs, and can occur during adolescence or adulthood. "In this study, we quantified the VV defects in the limbs of patients with primary lymphedema caused by mutations in GJC2 or FOXC2 and examined the earliest underlying mechanisms of VV failure caused by loss of those genes in mice." (PMID 28724617, 2017). "In individuals with primary lymphedema, owing to FOXC2 loss-of-function mutations, the cause of ectopic SMC recruitment was suggested to be a consequence of induction of PDGFB expression within the capillaries." (PMID 28851707, 2017). "Our findings elucidate a key contribution of FOXC1, complementary to FOXC2, in regulating lymphatic valve maturation and maintenance and provide additional insight into disease processes potentially associated with primary lymphedema." (PMID 32510325, 2020). "In the case of primary lymphedema, mutations in crucial lymphatic genes such as vascular endothelial growth factor receptor 3 (VEGFR-3) or forkhead box c2 (FOXC2) result in lymphatic hypoplasia and impaired function (Milroy disease, Meige disease)." (PMID 39682225, 2024). "Mutations identified in genes involved in the VEGF-C/VEGFR3 signaling pathway are commonly associated with primary lymphedema and other lymphatic malformations, which include mutations in critical transcription factors such as GATA2 and FOXC2." (PMID 32510325, 2020). "Mutations in the genes encoding FOXC2, (FOXC2) CX47 (GJC2), and CX43 (GJA1) cause primary lymphedema in man." (PMID 28724617, 2017). "Several de novo mutations have also been identified in other genes mutated in microcephaly (i.e. CTNNB1 and TUBA1A) and in primary lymphedema, such as SOX18, FOXC2 and VEGFR3." (PMID 25934493, 2015).
osteosarcoma (10 papers, 2016 to 2025). A usually aggressive malignant bone-forming mesenchymal neoplasm, predominantly affecting adolescents and young adults. "In osteosarcoma cell lines, we demonstrate that high levels of FOXC2 are associated with and required for the expression of osteosarcoma tumor-propagating cell markers." (PMID 27634875, 2016). "We analyzed whether FOXC2 expression is associated with expression of osteosarcoma stem cell markers CD133 and CD49f." (PMID 27634875, 2016). "For example, the circRNA PVT1 facilitates osteosarcoma metastasis through regulation of the miR-526b/FOXC2 axis, and circRNA-33186 participated in the pathogenesis of osteoarthritis through functioning as a sponge of miR-127-5p." (PMID 33506021, 2021). "For instance, circPVT1 has been found to promote osteosarcoma cells metastasis via directly targeting miR‐526b/FOXC2 and miR‐205‐5p/c‐FLIP, respectively." (PMID 33793089, 2021). "This anoikis-induced osteosarcoma cell invasiveness and metastasis to the lung are dependent on the ability of FOXC2 to induce CXCR4, a chemokine receptor responsible for tumour growth, invasion, angiogenesis, metastasis, relapse and therapeutic resistance." (PMID 32372224, 2020). "In another study, lncRNA ENST00000563280 and NR-036444 were found to interact with critical cancer genes such as ABCB1, HIF1A, and FOXC2 to modulate doxorubicin-resistance in osteosarcoma patients." (PMID 28122578, 2017). "The frequent detection of FOXC2 expression in human osteosarcomas suggests a possible involvement of FOXC2 in osteosarcoma pathology." (PMID 27634875, 2016). "We demonstrate that FOXC2 plays a critical role in osteosarcoma pathogenesis by enhancing the ability of tumor-propagating cells to metastasize and propagate tumors." (PMID 27634875, 2016). "Here, we report that the transcription factor forkhead box C2 (FOXC2) is frequently expressed in human osteosarcomas and is important in maintaining osteosarcoma cells in a stem-like state." (PMID 27634875, 2016). "We assessed the protein levels of FOXC2 in tumor tissue biopsies from patients diagnosed with Ewing's sarcoma, embryonal rhabdomyosarcoma, and osteosarcoma." (PMID 27634875, 2016). "To study the role of FOXC2 in osteosarcoma tumor propagation, we ectopically expressed FOXC2 in the SJSA1 osteosarcoma cell line, which has the lowest levels of endogenous FOXC2 compared to the U2OS and 143B cell lines." (PMID 27634875, 2016). "In this study, we demonstrated that FOXC2 is required for many of the properties and functions of osteosarcoma tumor-propagating cells, including resistance to anoikis, increased migratory and invasive capabilities." (PMID 27634875, 2016). "Positive FOXC2 staining was observed in primary bone lesions as well as in lung metastases from osteosarcoma patients." (PMID 27634875, 2016). "Reduced cell invasion and metastatic abilities of FOXC2 knockdown cell lines can be restored by overexpression of CXCR4, indicating that CXCR4 is a mediator of FOXC2 activity in osteosarcoma." (PMID 27634875, 2016). "Anoikis can also induce FOXC2 expression to facilitate cancer migration in osteosarcoma." (PMID 32372224, 2020). "Additionally, FOXC2 mRNA was upregulated in osteosarcoma samples in comparison to normal bone and in osteosarcoma lung metastases in comparison to primary tumors." (PMID 27634875, 2016). "In this study, we showed that FOXC2 regulates the expression of CXCR4 in osteosarcoma." (PMID 27634875, 2016). "In this study, we investigated the role of FOXC2 in osteosarcoma growth and metastasis." (PMID 27634875, 2016). "In osteosarcoma cell lines, we show that anoikis conditions stimulate FOXC2 expression." (PMID 27634875, 2016). "While positive FOXC2 immunostaining was observed in 3 of 7 Ewing's sarcomas and 1 of 2 embryonal rhabdomyosarcomas, 9 of 10 examined osteosarcomas were positive for FOXC2 with 7 tumors exhibiting strong staining and the remaining 2 tumors exhibiting weak staining." (PMID 27634875, 2016).
osteosarcoma (continued). "Because of the presence of FOXC2 in skeletal precursor cells and involvement in osteogenic differentiation, we hypothesized that FOXC2 may play a role in a tumor type with altered osteogenic differentiation, such as osteosarcoma." (PMID 27634875, 2016). "RARB has previously been identified in gene regulatory network of osteosarcoma, whereas FOXC1 (together with FOXC2) was shown to direct hypertrophic chondrocyte maturation and function toward primary ossification center formation and osteoblast recruitment." (PMID 40225119, 2025). "The direct interaction between FOXC2 mRNA and FOXC2-AS1 was demonstrated, for the first time, in human doxorubicin-resistant osteosarcoma cell lines." (PMID 33925370, 2021). "Studies performed in different osteosarcoma cell lines and tissue samples have shown that the expression levels of both FOXC2 and FOXC2-AS1 were upregulated and that FOXC2-AS1 controlled FOXC2 protein production, stabilizing its transcript." (PMID 33925370, 2021). "In FOXC2 knockdown cell lines, we show that CXCR4, a downstream target of FOXC2, can restore osteosarcoma cell invasiveness and metastasis to the lung." (PMID 27634875, 2016). "Forced re-expression of CXCR4 in the 143B FOXC2 knockdown cells restored their invasive capabilities in vitro and in vivo, indicating that CXCR4 is a downstream target and a functional mediator of FOXC2 signaling in osteosarcoma." (PMID 27634875, 2016). "To assess the potential involvement of FOXC2 in the metastatic capability of osteosarcoma, we analyzed the effects of culture conditions in the osteosarcoma cell lines 143B (exhibits high endogenous levels of FOXC2) and in SJSA1 and U2OS (exhibit moderate endogenous levels of FOXC2)." (PMID 27634875, 2016). "Examination of the relative expression of FOXC2 in a diverse range of cancer cell lines in the Cancer Cell Line Encyclopedia (CCLE) expression profile database showed that FOXC2 mRNA levels were elevated in several cancer types, including osteosarcoma (data not shown)." (PMID 27634875, 2016).
Obesity (9 papers, 2010 to 2025). Accumulation of substantial excess body fat. "Genes involved in angiogenic patterning affect adipose tissue function; for example, forkhead box C2 (FOXC2) in adipose tissue affects angiogenesis and vascular patterning, and is associated with adipose tissue function and obesity." (PMID 35857195, 2022). "The article also shows data on the effect of treatments of differentiated podocytes with various factors associated with obesity and diabetes on the expression level of FOXC2." (PMID 26904714, 2016). "We hence excluded patients with diabetes and obesity from this study population to get an unbiased data of FoxC2 polymorphism pattern in patients with CVD alone." (PMID 24608096, 2014). "FoxC2 polymorphisms and abnormal protein expression have been implicated with insulin sensitivity in patients with obesity and diabetes mellitus." (PMID 24608096, 2014). "FOXC2 has lately been implicated in diabetes and obesity as well as mitochondrial function and biogenesis and also as a regulator of mtTFA/Tfam." (PMID 22098677, 2011). "Further, in RIIβ mice, pRb-deficient mice and in mice overexpressing FOXC2, protection against diet-induced obesity is accompanied by an increased RIα/RIIβ ratio, rendering PKA somewhat more sensitive to cAMP, which is accompanied by an increased occurrence of brown adipocytes in WAT." (PMID 20613988, 2010). "Early growth response protein 1 (Egr-1)—a negative regulator of FOXC2—is highly expressed in obesity and IR models." (PMID 41404514, 2025). "In this context, Egr-1 null mice would be protected against obesity-related complications, such as elevated circulating TG levels, by a mechanism possibly mediated by FOXC2, increasing energy expenditure and altering mitochondrial function." (PMID 27478511, 2016). "Of note, Foxc2 mRNA levels were also increased in epididymal white adipose tissue of WT mice fed a high-fat diet compared to individuals fed a standard diet, suggesting that FOXC2 acts as a metabolic regulator in protection against diet-induced obesity and insulin resistance." (PMID 32477160, 2020).
prostate carcinoma (9 papers, 2018 to 2024). A carcinoma that arises from epithelial cells of the prostate gland. "In our study, we have demonstrated that FOXC2 is strongly expressed in primary, metastatic and castration resistant prostate cancers, and is a strong predictor of outcome, of potential importance for prognostication and targeted therapy." (PMID 31464093, 2019). "Here we provide a rationale for applying FOXC2 as a biomarker in prognostication and novel targeted therapy in prostate cancer and lend support to the significance of epithelial–mesenchymal phenotypes in localised and advanced disease." (PMID 31464093, 2019). "On this background, our findings of highly increased FOXC2 expression in primary, metastatic and castration resistant prostatic carcinomas, with a strong link to poor outcome, make FOXC2 attractive for targeted therapy." (PMID 31464093, 2019). "Notch activation drives FOXC2-dependent metastasis in PTEN-null prostate cancer mice." (PMID 37124622, 2023). "Using the novel small molecule inhibitor of FOXC2 in prostate cancer overexpressors may possibly relieve these difficulties." (PMID 31464093, 2019). "AR is reported to be suppressed by N-Myc in NEPC and the p38MAPK/FOXC2/Zeb1 pathway in prostate cancer stem-like cells (PCSCs), and inhibition of FOXC2 can reduce stem cell properties and restore AR/PSA expression and also sensitivity to docetaxel in DU145 cells." (PMID 29555975, 2018). "Almost all of the FOX genes were differentially expressed in prostate cancer, prostate carcinoma, and metastatic prostate cancer, except FOXA3, FOXB2, FOXC2, FOXI2, FOXI3, FOXP4, and FOXR1." (PMID 36292640, 2022). "In another in vitro study, insulin via the upregulation of Forkhead Box Protein C2 (FOXC2) promotes migration and invasion of prostate cancer cells and activation of insulin signaling pathway and inhibition of PI3K and MAPK pathways lead to epithelial-mesenchymal transition." (PMID 33921222, 2021). "FOXC2 was recently highlighted as a novel therapy target in prostate cancer, but survival data on FOXC2 are lacking." (PMID 31464093, 2019). "FOXC2 and factors signifying EMT or its intermediate states may prove important as biomarkers for aggressive disease and are potential novel therapy targets in prostate cancer." (PMID 31464093, 2019). "However, there are still no available survival data on FOXC2 in prostate cancer." (PMID 31464093, 2019).
hepatocellular carcinoma (8 papers, 2018 to 2025). A malignant tumor that arises from hepatocytes. "FOXC2 serves as a prognostic biomarker and facilitates tumor growth and invasive potential in hepatocellular carcinoma." (PMID 40746552, 2025). "For instance, in esophageal squamous cell carcinoma (ESCC) and hepatocellular carcinoma, FOXC2 serves as a prognostic marker, playing a role in tumor growth and invasion." (PMID 40746552, 2025). "The results indicated that the high expression of FOXC2 in hepatocellular carcinoma (HCC) is associated with malignant degree and poor prognosis, thereby suggesting that FOXC2 is an important prognostic factor in HCC." (PMID 34484336, 2021). "Overexpression of FOXC2 was related to poor prognosis of hepatocellular carcinoma.FOXC2 activated YAP signal pathway and enhanced the glycolysis in nasopharyngeal carcinoma cells." (PMID 32222147, 2020). "Studies in hepatocellular carcinoma also showed that transcriptional expression of the Angpt2 promoter was directly targeted by FOXC2 and that Angpt2 knockdown abolished FOXC2-facilitated angiogenesis and tumor growth, suggesting that FOXC2 promotes tumor progression via regulation of Angpt2." (PMID 36230774, 2022). "The expression of FOXC2 and EMT-related markers was evaluated by immunohistochemistry in 84 cases of hepatocellular carcinoma." (PMID 29801468, 2018). "FOXC1 and FOXC2 were required for intestinal regeneration by stimulating paracrine CXCL12 and Wnt signaling, and FOXP1 downregulation inhibited G1/S phase cell cycle arrest by inducing the proliferation of hepatocellular carcinoma." (PMID 38192721, 2023).
nasopharyngeal carcinoma (8 papers, 2018 to 2025). A carcinoma arising from the nasopharyngeal epithelium. "The first observation was in nasopharyngeal carcinoma, in which FOXC2 increases glycolysis in cancer cells via the FOXC2-YAP (Yes-Associated Protein) axis to up-regulate hexokinase 2 and ultimately facilitates tumor survival and progression." (PMID 30360388, 2018). "In nasopharyngeal carcinoma, forkhead box C2 (FOXC2) can activate YAP and regulate HK2 positively to promote glycolysis." (PMID 33607990, 2021). "Moreover, FOXC2 promotes chemoresistance in nasopharyngeal cancer by inducing epithelial-mesenchymal transition, while also modulating the YAP signaling pathway and enhancing glycolysis." (PMID 40746552, 2025). "Functionally, FOXC2 acts as a bridge to interact with YAP and TEAD, and forms a FOXC2-YAP-TEAD complex, which leading to activation of HK2 and eventually promote glycolysis in nasopharyngeal carcinoma cells." (PMID 30176928, 2018).